TNF (tumor necrosis factor)
Diseases named in the same sentence as TNF in open-access papers (continued):
Sharing a sentence is not in itself a finding about the gene and the disease.
tumor (continued). "Multiple favorable changes in the immune system of BC patients have been reported due to PA, including in T helper lymphocytes and CTL populations, T regulatory cells, NKs, monocytes, tumor-associated macrophages, IL-6, and tumor necrosis factor (TNF-α)." (PMID 33379177, 2020). "For instance, tumor necrosis factor-α (TNF-α) secreted by tumor-associated macrophages induces activation of the SNAIL promoter and promotes the EMT process." (PMID 33256814, 2020). "TNFα is the major inflammatory cytokine produced by adipose tissues, tumor-associated fibroblasts, and various inflammatory cells infiltrating the tumor tissues." (PMID 33053908, 2020). "An example of immunotherapy is to manipulate the microenvironment by inducing tumor necrosis factor (TNF) production by tumor-associated myeloid cells which ultimately leads to tumor eradication." (PMID 32582143, 2020). "Pro-inflammatory cytokines (TNF-α and IL-1β) induced by tumor-associated immune cells play crucial roles in the migration and differentiation of MSCs within the tumor." (PMID 32121074, 2020). "Next, we tested if human tumor-infiltrating lymphocytes (TILs) were susceptible to TNF-mediated cell death." (PMID 32292509, 2020). "Under these conditions, NK cells show cytotoxicity and are producers of proinflammatory cytokines such as IFN-γ, TNF-α, IL-13, IL-10, and GM-CSF, when there is contact with tumor cells susceptible to be recognized." (PMID 33276556, 2020). "It was reported that intra-tumoral levels of TNF are likely insufficient to regress tumor and chronic exposure to TNFα increases the risk of tumor development and progression." (PMID 33352869, 2020). "In fact although associated with tumor-induced chronic inflammation, TNF if produced at high doses becomes a key factor in mediating tumor-rejection." (PMID 31281314, 2019). "Inhibition of RIPK1 did not interfere with selective accumulation of L19-TNF into neoplastic lesions, where high local concentrations of TNF caused onset of tumor vascular shutdown and selective hemorrhagic necrosis." (PMID 31803362, 2019). "Inflammation‐associated cytokines (including interleukin‐1β, IFN‐γ, and TNF‐α) in tumour microenvironment induce CCA cells to express iNOS that catalyses the production of NO." (PMID 30394682, 2019). "For instance, although TNF-α causes necrosis in some types of tumors, it promotes growth of other types of tumor cells." (PMID 31700580, 2019). "In RIP1‐Tag5 tumours, which were devoid of immune infiltrates, treatment with TNFα‐CSG (5 daily i.v. injections of 2 or 5 μg) caused a significant influx of CD8+ and CD4+ T cells and macrophages." (PMID 31709774, 2019). "Although TNF is potent in causing tumor necrosis, the firsttwo clinical trials of TNF-like molecules for cancer therapy failed because oflethal inflammatory shock syndrome and fulminant liver toxicity." (PMID 31444476, 2019). "Another interesting notion is the implication of tumor-associated TNF in the dedifferentiation of cancer cells." (PMID 31417576, 2019). "Tumor cells produced TNF-α to endorse tumor cell survival through the induction of genes encoding NFκB-dependent anti-apoptotic molecules." (PMID 31726654, 2019). "TNF-α is a hallmark inflammatory cytokine secreted by LPS activated macrophages that is critical for activating the adaptive immune response and anti-tumor T cell immunity." (PMID 31075929, 2019). "The present study confirmed that high preoperative serum IL6, IL8, and TNF-α levels were distinctly correlated with the postoperative tumor recurrence risk of HCC patients." (PMID 31781194, 2019). "Despite of its anti-tumor properties, the systemic administration of TNF-α in a sufficient dose is associated with a high toxicity." (PMID 31179236, 2019). "Anti-tumor: NCR+ILC3s produce IL-22, TNFα, IL-8 and IL-2 to activate endothelial cells forming protective tumor-associated tertiary lymphoid structures." (PMID 32117199, 2019).
tumor (continued). "Although associated with tumor-induced chronic inflammation, TNF, if produced at high doses, becomes a key factor in mediating tumor rejection." (PMID 31281314, 2019). "LM-Dox activation of tumor-associated macrophages to release TNF-α was evaluated by western blot and immunofluorescence assays." (PMID 31660078, 2019). "There are several types of DC-vaccines, being the most frequently used the reinfusion of ex vivo derived DC pulsed with tumor-associated antigens (TAAs) or tumor cell lysates and stimulated with TNF-α, IL-1β, IL-6, and prostaglandin E2 (PGE2)." (PMID 31998254, 2019). "High concentrations of TNFα, presumably derived from tumor-associated immune cells, were detected within lysates of tumors resected from mice six hours after administration of a single dose of saline, GDC-0152 or LCL161." (PMID 31521127, 2019). "One of the key factors involved in inflammation-mediated cancers is the tumor necrosis factor alpha (TNFα), which is implicated in selective destruction of tumor blood vessels and hemorrhagic necrosis." (PMID 31591350, 2019). "Tumor-associated macrophages (TAMs) help tumor cell growth by releasing several pro-inflammatory cytokines, such as TNFα and IL2317." (PMID 32695310, 2019). "In this scenario, the effect of MLN4924 on the interplay of tumor-associated TNF and cells of the tumor microenvironment is presumably also of relevance." (PMID 31406107, 2019). "Other cytokines and growth factors such as tumor necrosis factor (TNF)-α have also been shown to participate in the development, tumor growth and metastasis of LC in patients with underlying respiratory conditions." (PMID 31455338, 2019). "Simultaneously, LM-Dox induced secretion of TNF-α in tumor-associated macrophages, which increased the antitumor activity of Dox." (PMID 31660078, 2019). "It promotes tumor growth and higher serum levels of TNF-α have been reported to be associated with poor prognoses in cancer patients." (PMID 31192215, 2019). "Other apoptosis-associated proteins, such as TFIP8, a tumor suppressor that regulates TNF-mediated apoptosis via inhibition of caspase-8 were also upregulated in HS578T/NOD1." (PMID 30791886, 2019). "Several studies have shown that the overexpression of antiapoptotic proteins including cIAP-2, cFLIPs, Bcl-2, and Bcl-XL in tumor cells has been associated with the inhibition of TNF-α-induced apoptosis." (PMID 31766230, 2019). "Within the tumor microenvironment, TNF is produced by tumor associated macrophages and is constitutively produced in cancer cells." (PMID 31174326, 2019). "TNF-α is associated with cell-mediated immune response and confers immunity against harmful agents including bacteria, viruses, and even tumor cells." (PMID 31126046, 2019). "Simultaneously, LM-Dox induces secretion of TNF-α by tumor-associated macrophages to increase the cytotoxicity of Dox." (PMID 31660078, 2019). "For example, tumor cell necrosis after chemotherapy causes the release of tumor necrosis factor, one of the main factors involved in liver cell damage and even hepatic necrosis." (PMID 31077212, 2019). "Interleukins, such as IL-6 and tumor necrosis factor (TNF)-α, and tumor-associated factors can induce the increased expression of lnc-CHOP in mouse MDSCs." (PMID 31404149, 2019). "A number of inflammatory mediators including the cytokines TGFβ, TNFα, IL-1, IL-6, and IL-8, and several chemokines produced by the tumor-associated cells are also EMT-inducers, leading to inflammatory cytokine-induced EMT (ICI-EMT)." (PMID 31557902, 2019). "In SKOV-3 cells, PD-L1 was variably found in the surface and cytoplasm, and its expression was correlated with high levels of TNF-α, IL-10, and IL-6 released from tumor-associated macrophages (TAMs)." (PMID 31861351, 2019). "Our CSG‐based targeting strategy was employed to achieve high levels of TNFα locally and specifically associated with tumour ECM." (PMID 31709774, 2019).
tumor (continued). "TNF is implicated with cellular proliferation in hepatocarcinogenesis and persistent IL-6 is associated with tumor development." (PMID 30606143, 2019). "As a result, authors observed an increased secretion of IL-6 and tumor necrosis factor-α (TNFα) by tumor-associated macrophages, which determines a pro-tumoral inflammatory response promoting cancer growth and metastasis." (PMID 30884898, 2019). "In this study, the production of TNF-α in cancer cells was enhanced by PEV, suggesting that TNF-α directly caused tumor necrosis and suppressed tumor growth." (PMID 31467867, 2019). "Tumor necrosis factor alpha (TNF-α) is an important cytokine, and cytotoxin triggers have been implicated in tumor regression, septic shock, and cachexia." (PMID 30600678, 2019). "In summary, the present study demonstrated that ACSL1 plays a crucial role in the regulation of TNFα mediated excessive production of GM-CSF associated with the inflammatory process that is involved in tumor growth." (PMID 31581558, 2019). "TNFα is a tumor-promoting cytokine and TNF-deficiency in stromal cells significantly decreased MCP-1 production by tumors of the mouse Lewis lung cancer cells." (PMID 31888216, 2019). "Tumor associated macrophages were shown to produce TNF-α that induces CXCR4 expression, thus promoting SDF-1 mediated pro-tumorigenic effects." (PMID 31921870, 2019). "Our findings show that high preoperative serum IL6, IL8, and TNF-α levels were significantly correlated with the postoperative tumor recurrence risk of the HCC patients." (PMID 31781194, 2019). "This was associated with the ability of TNF to induce activation-induced cell death (AICD) of CD8+ T cells thus promoting tumor growth and impeding response to anti-PD-1." (PMID 31727152, 2019). "The growth of primary tumours and metastases is strongly inhibited in C3-deficient mice and is associated with increased numbers of IFNγ+/TNFα+/IL10+ CD4+ and CD8+ T cells." (PMID 30841875, 2019). "TNF-α is one of the cytokines secreted in inflammatory processes and associated closely with tumor progression." (PMID 31142737, 2019). "Tumor necrosis factor-alpha can cause hemorrhage and necrosis of tumor cells, directly kill tumor cells, cause local inflammatory reaction, and promote the killing ability of monocyte macrophages." (PMID 31256187, 2019). "The targeted delivery of TNF causes a rapid and selective hemorrhagic tumor necrosis in mouse models of cancer and in patients." (PMID 31803362, 2019). "In vitro cytotoxicity and IFN-γ/TNF-α secretion were measured by flow cytometry-based cytotoxicity assay and enzyme-linked immunosorbent assay, respectively, after direct co-culture with tumor cells." (PMID 31126350, 2019). "GSK’963, a potent small molecule inhibitor of RIPK1, was tested in tumor-bearing mice for its ability to reduce acute toxicity associated with TNF signaling." (PMID 31803362, 2019). "Finding ways to increase production of this cytokine can potentiate the efficacy of immunotherapy, yet selective targeting of TNF in the tumor mass as well as management of the toxicity associated with such approaches remain a concern." (PMID 31417576, 2019). "On the other hand, deregulated TNF signaling has been implicated in several human ailments, including inflammatory bowel disorders and neoplastic diseases." (PMID 31134075, 2019). "Adipocytes produce pro-inflammatory adipokines and cytokines [including CCL2, interleukin-6 (IL-6), and TNFα], which increase inflammation and metastatic risk, supporting tumor survival." (PMID 31788448, 2019). "It has previously been shown that upon binding to TWEAK, Fn14 can recruit a cellular inhibitor of apoptosis protein 1- (cIAP1-) TNFR-associated factor 2 (TRAF2) complex and sensitize tumor cells to TNF-α." (PMID 31885495, 2019). "CCL20-producing tumor associated macrophages were associated with tumor progression and worse survival possibly because they co-expressed pro-tumor cytokine TNF and pro-angiogenic VEGF-A." (PMID 30899263, 2019).
tumor (continued). "Although kidney expression of the pro-inflammatory cytokines CXCL1 and TNF-α increased in IL-33 deficient mice, surprisingly, tumor weight, volume, and growth were significantly decreased and the effect of cis-platin on tumors was greatly enhanced." (PMID 30205617, 2018). "Stimulation with IFN-γ plus TNF-α was also highly efficient in promoting cross-presentation of cell-associated tumor antigens by human cDC1 (CD141+ DCs)." (PMID 29904904, 2018). "When tumor-associated macrophages secrete TNF, the activation of Wnt/ β-catenin signaling pathway is promoted and this leads to greater tumor development." (PMID 29696001, 2018). "These two publications suggest that NLRX1 functions as a tumor suppressor by decreasing cancer-associated inflammation (IL-6 and TNFα) through effects on NF-κB signaling." (PMID 29535731, 2018). "Further, cytokines secreted by adipose tissue like IL-1β, IL-6 and IL-8 have been implicated in tumor progression by stimulating tumorigenic pathways in cancer cells, such as TNFα and NF-κB signaling." (PMID 29930291, 2018). "Given the inability to translate the profound anti-tumor effects observed in animal studies to human studies, some researchers have explored localized administration of TNF-alpha in hopes of avoiding adverse effects associated with systemic use." (PMID 30170620, 2018). "In invasive BC, tumor-associated macrophages (TAMs) produce many proinflammatory cytokines, mainly, tumor-necrosis factor (TNF)-α." (PMID 30059519, 2018). "Further on, reduced TNFα secretion seems to be associated with the inability of tumor infiltrating lymphocytes and macrophages to directly kill the LL/2-luc-M38 tumor cells." (PMID 30647851, 2018). "Further on, reduced TNFα is described to lead to impaired recruitment of lymphocytes in the tumor and therefore is associated with enhanced tumor development." (PMID 30647851, 2018). "Underlining this, loss of TNFR2 results in a large increase of TNF-associated tumor cell death and a significant halt of tumor growth in lung cancer." (PMID 29892300, 2018). "The enhanced checkpoint blockade responsiveness in DIO mice was associated with significantly increased CD8+ tumor- infiltrating lymphocytes (TILs), as well as increased TNFα and IFNγ-production by CD8+ T cells." (PMID 30400822, 2018). "Cytokines implicated in promoting an anti-tumor effect include TNF-α, IL-1, − 4, − 6, IL-17 and IFN-γ." (PMID 30305172, 2018). "Multiple mechanisms are believed to be associated with tumor vascular damage by TNF-alpha, including induction of release of von Willebrand Factor, which is a known anti-coagulant, as well as endothelial cell activation leading to thrombosis." (PMID 30170620, 2018). "In vivo, we demonstrated that novel intravenously administered DAB-Lf dendriplex encoding TNFα led to tumor eradication of 70% of PC-3 and 50% of DU145 tumors." (PMID 29493296, 2018). "TNF-α gene expression is strongly linked to tumor promotion by the okadaic acid class compounds in rodents." (PMID 30341686, 2018). "Reduced TNFα secretion is also linked to the inability to suppress tumor cell proliferation and to induce tumor progression." (PMID 30647851, 2018). "Cytokines such as TNF are well known pro-inflammatory cytokine associated with tumor proliferation and invasion." (PMID 30532215, 2018). "Previous studies have implicated several cytokines, including IFNɤ, TNFα, and IL-2, as possible regulators of PD-L1 expression on the surface of several tumor cells, and IFNɤ has been thought as a strong inducer of PD-L1 expression in cancer cells." (PMID 30400941, 2018). "The role of TNFα and IL-6 as master regulators of tumor-associated inflammation and tumor-promoting functions makes them promising targets for adjuvant anti-cancer therapy." (PMID 29946544, 2018). "For example, skin carcinogenesis is reduced in tumor necrosis factor α (TNFα) deficient mice, suggesting a role for this cytokine in the early stages of tumor development." (PMID 30559930, 2018).
tumor (continued). "Although studies manipulating tumor-associated monocytes/macrophages show only small increases in M1-like cytokines and chemokines (such as TNFα, IL1β etc.), the greatest increase was seen following monocyte-specific NRP1 ablation." (PMID 30479695, 2018). "The neoplasms occurred late after anti-TNF initiation, and infliximab was associated with a shorter time to malignancy compared to etanercept." (PMID 29540190, 2018). "Increased TNFα levels are detected in the microenvironment of CRC and vice versa in mouse models for CAC development; TNFα levels are linked with increased leukocyte infiltration and tumor formation." (PMID 30591653, 2018). "A further investigation led to identify Alistipes shaii as a bacterial species positively associated with TNF production by tumor-associated myeloid cells." (PMID 29789015, 2018). "Pro-inflammatory cytokines such as IL-6, IL-1β and TNF are produced by a variety of cell types in a cancer including the tumor cells themselves, cancer-associated fibroblasts, and tumor-associated macrophages." (PMID 29883385, 2018). "Along these lines, Drosophila investigations have correlated the expansion of genetically induced tumours with the recruitment of tumour associated hemocytes (TAHs) and their production of Eiger (TNF-α in flies)." (PMID 29854765, 2018). "Chronic inflammation has been confirmed to be strongly associated with tumor invasion, migration and metastasis through increased secretion of pro-inflammatory cytokines, such as IL-2, IL-6, tumor necrosis factor-α and so forth." (PMID 30513726, 2018). "After GET of pVAX not only IFN β, but also TNF α mRNA was increased, which is probably associated with an increased proportion of necrosis and consequently the highest tumor growth delay and complete tumor regression rate." (PMID 29382170, 2018). "Here we show that in premature senescent tumor cells trabectedin causes a marked decrease in the expression of proinflammatory cytokines (IL-6, IL-8, TNF-alpha), which play critical roles in tumor growth and metastasis." (PMID 29731994, 2018). "This is also supported by evidence that the addition of TNFα to tumor cells increases their susceptibility to Fas-mediated killing by effector cells." (PMID 29464051, 2018). "Tumor-associated macrophages and Th2 cell-produced tumor necrosis factor (TNF)-α have been reported to promote cancer stem cell (CSC) plasticity." (PMID 30486830, 2018). "TNF-α-induced hypermethylation of PRKCDBP was associated with NF-κB activation in the tumor suppressive effect of PRKCDBP in colorectal cancer." (PMID 29467412, 2018). "In response to iC3b-positive tumor cells, β-glucan-primed leukocytes produced cytokines including TNF-α, IFN-γ, IFN-α, and IL-6, which are associated with tumor cell destruction." (PMID 29535722, 2018). "Egr expression is induced in tumours and tumour-associated immune cells, much like mammalian TNF-α, which is detected in tumour cells as well as macrophages and T lymphocytes." (PMID 29725601, 2018). "Normal levels of TNF-α can regulate the immune response, work as anti-infection, promote tissue repair, and cause tumor cell apoptosis." (PMID 29541141, 2018). "As expected, in subcutaneous tumor models, macrophage TgMGLL largely potentiated mRNA levels of TNFα, IL-6, and IFNγ in tumor-associated CD8+ T cells, and this effect was prevented by additional macrophage TgCB2." (PMID 29968710, 2018). "Due to the higher expression of TNFR2 relative to TNFR1 in tumor and tumor-associated cells, TNF is likely to have a tumor-promoting function instead of an inhibitory impact." (PMID 29892300, 2018). "αvβ3- and αvβ5-associated angiogenesis are respectively dependent on tumor cell-secreted fibroblast growth factor (bFGF)/tumor necrosis factor (TNF)α and VEGF through an amplification loop leading to αvβ3/αvβ5 overexpression on EC." (PMID 30304861, 2018).